CLOCK (clock circadian regulator)
Diseases named in the same sentence as CLOCK in open-access papers (continued):
Sharing a sentence is not in itself a finding about the gene and the disease.
Obesity (continued). "Observational studies in small sample populations have shown that polymorphisms in the CLOCK gene are associated with predisposition to obesity, and that two single nucleotide polymorphisms in BMAL1 are associated with Type 2 Diabetes (T2D) and hypertension." (PMID 30935034, 2019). "The links from genetic variants to physiologic functions are most likely less thanpredicted, a study identified increased weight and obesity and features of metabolicsyndrome as characteristics of CLOCK-deficient mice." (PMID 29767668, 2018). "In some of these studies, single nucleotide polymorphisms in CLOCK genes were associated with increased obesity and metabolic syndrome incidence." (PMID 28645331, 2017). "Further studies regarding the potential interactions between restricted sleep and CLOCK polymorphisms influencing the development of obesity are needed." (PMID 28645331, 2017). "Single nucleotide polymorphisms in KAT13D (CLOCK) gene are associated with obesity and weight loss success in humans." (PMID 26925174, 2016). "Some variants in CLOCK and other related genes modify the individual risk of developing metabolic diseases, such as obesity or T2DM." (PMID 26927084, 2016). "CLOCK SNPs have been associated with nonalcoholic steatohepatitis, metabolic syndrome, small dense low-density lipoprotein levels, obesity, and T2DM (260, –, 264)." (PMID 27763782, 2016). "In humans, various CLOCK single nucleotide polymorphisms (SNPs) (i.e. rs1464490, rs3749474, rs4864584, rs4580704 and rs18012602) have also been associated with obesity, hyperglycemia and greater prevalence of T2D in cross-sectional studies." (PMID 26739996, 2016). "Polymorphisms in the gene CLOCK have been associated with obesity parameters, such as cholesterol levels and increased small dense LDL, in humans." (PMID 25365257, 2014). "Genetic variations in the CLOCK (Circadian Locomotor Output Cycles Kaput) were associated with overweight and obesity, food intake and metabolic syndrome traits." (PMID 25089907, 2014). "For example, the genetic variability in the CLOCK gene has been associated with increased weight and obesity, and loss of the ARNTL gene functions was shown to result in development of metabolic syndrome in knock-out rats." (PMID 23527142, 2013). "CLOCK is the product of the CLOCK gene that in both, genetic and experimental studies has been associated with obesity." (PMID 23251369, 2012). "The CLOCK gene has also been proposed to be involved in the metabolic syndrome, which involves obesity and increased the risk for diabetes and heart disease." (PMID 20180986, 2010). "Besides, genetic mutants in CLOCK genes have been reported to be associated with metabolic syndrome and obesity in CLOCK mutant mice." (PMID 40024983, 2025). "The CLOCK CC genotype interacts with disinhibition, an important driver for this gene-environment interaction, associated with a high anthropometric measurement and obesity." (PMID 39203789, 2024). "In addition, the minor allele (G) of the CLOCK rs4580704 SNP, associated with obesity, has been shown to be more prevalent among late eaters (after 3:00 pm) compared to early eaters (before 3:00 pm) and has been linked to consumption of a later lunch." (PMID 39064774, 2024). "In addition, the SIRT1 rs1467568 and CLOCK 3111T > C combined genotype was associated with the evening chronotype and weight loss resistance in a behavioral therapy treatment for obesity." (PMID 36768893, 2023). "Moreover, significant gene–sleep interactions were detected between the midpoint of sleep and the TAS2R38-rs713598 (p = 0.032), FTO-rs9939609 (p = 0.037), and CLOCK-rs4580704 (p = 0.004) polymorphisms which played a role in determining obesity phenotypes." (PMID 36771415, 2023). "E2F4 and CLOCK are associated with prognosis in patients with diabetes mellitus and obesity." (PMID 36837510, 2023). "Indeed, CLOCK rs4580704 was linked to cardiometabolic risks such as metabolic syndrome, obesity, diabetes, and cardiovascular diseases." (PMID 37242182, 2023).
Obesity (continued). "Furthermore, CLOCK rs4580704 was associated with metabolic syndrome, diabetes, obesity, and cardiovascular diseases." (PMID 37242182, 2023). "Secondarily, authors hypothesized that genotypes homozygous or heterozygous for the 3111C CLOCK allele would be associated with obesity compared with the homozygous genotype." (PMID 36159463, 2022). "In the present study, conducted in a population of subjects with overweight/obesity, we observed an association between PM exposure measured in the week before the blood drawing and the methylation of circadian cycle genes (i.e., CLOCK, CRY1, CRY2, PER1, PER2, and PER3)." (PMID 33513987, 2021). "Thus far, few studies have assessed the association of the CLOCK gene with obesity in the pediatric population." (PMID 32785234, 2020). "In addition, the CLOCK gene region (4q12) was linked to obesity in a microsatellite-based whole-genome linkage analysis." (PMID 28645331, 2017). "Besides the 3111 T > C SNP, the rs1554483, rs6843722, rs6850524, and rs4864548 CLOCK gene variants alone or combined in haplotypes have been linked to the individual susceptibility to obesity." (PMID 28645331, 2017). "Together, these studies highlight the relationship between CLOCK variants and T2DM and obesity-related traits, but they also point to the diet as potential modulator of this relationship and suggest that CLOCK variants should be included in SNP panels for personalized nutrition." (PMID 26927084, 2016). "Therefore, in future studies to be conducted prospectively in different groups, there is a need to evaluate the effect of interaction of CLOCK variants' interaction with eating jetlag on obesity and metabolic parameters and to understand the underlying mechanisms." (PMID 39744380, 2024). "In conclusion, our study, for the first time, shows an association between CLOCK genetic variants and obesity in pregnant women, also strengthening the link between the rs1801260A/rs4864548-A/rs3736544-G haplotype of the core clock gene and the susceptibility to obesity." (PMID 38612648, 2024). "Furthermore, CLOCK gene variants have also been associated with the risk of obesity." (PMID 36676985, 2022). "As there is a debate concerning the role that clock genes could have in connecting drug abuse-related behaviors and obesity/metabolic syndrome, the expression of genes encoding CLOCK, BMAL1, PER2 and CRY1 were also analyzed within the hippocampus (HIP) and the prefrontal cortex (PFC)." (PMID 31546853, 2019). "CLOCK gene mutant animals have shown alterations in the normal pattern of daytime feeding and developed hyperphagia and, consequently, obesity." (PMID 40787788, 2025). "Circadian abnormalities, regulated by key clock genes such as CLOCK and BMAL1, are well-documented in depressive disorders and significantly impact metabolic processes associated with obesity." (PMID 40225722, 2025). "Further research is required to examine additional CLOCK SNPs and other circadian genes in adolescents to understand the relationship between the circadian system and the development of obesity." (PMID 39744380, 2024). "This study investigates the relationship between six obesity-related genes (CLOCK, FTO, GHRL, LEP, LEPR, MC4R) and their impact on BMI, WC, HC, WHR, and emotional eating behavior in 220 Romanian adults." (PMID 39203789, 2024). "Given that WC and WHR are useful predictors of abdominal obesity, this study highlights the potential role of the CLOCK, FTO, and LEP gene variants in increasing the risk of this type of obesity, which is often associated with cardiovascular disease." (PMID 39203789, 2024). "Specifically, CLOCK/CC, FTO/AA, and LEP/AA genotypes were strongly associated with higher obesity metrics and emotional eating scores, while GHRL/TT and MC4R/CC were linked to increased BMI and WHR." (PMID 39203789, 2024). "For example, animals with a genetic circadian disruption, such as the mutation of CLOCK and the deletion of BMAL1, are prone to obesity and metabolic syndrome." (PMID 37293491, 2023).
Obesity (continued). "Lastly, previous studies have found differences in the obesity risk related to TAS2R38-rs713598, FTO-rs9939606, and CLOCK-rs4580704, which is consistent with our findings." (PMID 36771415, 2023). "They discovered that CLOCK is involved in obesity-induced disordered fibrinolysis by tissue-dependently regulating PAI-1 gene expression." (PMID 37626963, 2023). "In the male VLFC group, the minor allele carriers of CLOCK rs9312661, CRY2 rs7951225, and the GG genotype of CRY1 rs11113192 showed increased risks of obesity; however, significances were diminished after the Bonferroni correction." (PMID 35276838, 2022). "Chronodisruption, including CLOCK mutant models, leads to dysbiosis and promotes obesity, while fasting, intermittent fasting or time-restricted feeding help re-set the balance." (PMID 36501110, 2022). "The results of our study support the notion that CLOCK locus (rs1801260) influences obesity-related behaviors, such as reduced sleep duration, evening-type, and appetite regulators such as plasma ghrelin." (PMID 35655162, 2022). "Single nucleotide polymorphisms (SNPs) of CLOCK and ARNTL influence body weight control, the development of obesity, and susceptibility to metabolic diseases." (PMID 35276838, 2022). "In humans with obesity, 24-h gene expression of CLOCK, BMAL1, PER1, CRY2, and REV-ERBα in adipocytes is disturbed." (PMID 35111358, 2022). "In humans, genetic variants of CLOCK and another core clock gene BMAL1 are associated with susceptibility to obesity and type 2 diabetes, respectively." (PMID 33676029, 2021). "The agent metformin, an inhibitor of mTOR activity, can prevent such processes during obesity in experimental mouse models and can reverse the loss of SIRT1 function during inhibition of the circadian components CLOCK and BMAL1." (PMID 34590471, 2021). "Polymorphisms of human clock genes, such as ARNTL, circadian locomotor output cycles kaput (CLOCK), CRY2, and nuclear receptor subfamily 1, group D, member 1 (NR1D1), have been linked to obesity or some other features of metabolic syndromes." (PMID 33424933, 2020). "The high prevalence of obesity in menopausal women was the reason for choosing this critical period of life to study the effect of SNP 3111T/C in the CLOCK gene on lipid outcomes." (PMID 35366265, 2020). "While CLOCK expression levels are increased with HDF-induced obesity, peroxisome proliferator-activated receptor (PPAR) alpha increases the transcriptional level of brain and muscle ARNT-like 1 (BMAL1) in obese subjects." (PMID 31489938, 2019). "However, given that cross-sectional studies may be confounded by other factors related with obesity and other phenotypes concurrently associated with T2D, our longitudinal study provides a higher evidence level for the contribution of the CLOCK gene to T2D incidence." (PMID 26739996, 2016). "The positive association between CLOCK and LDL levels in our study is in accordance with the link between the gene CLOCK and obesity in humans." (PMID 25365257, 2014). "BMAL1 and CLOCK dysfunction leads to hyperphagia, obesity and metabolic syndrome including hyperlipidemia, hepatic steatosis, hyperleptinemia and hyperglycemia." (PMID 20706650, 2010). "Dysregulation of the BMAL1/CLOCK coupling may be the key to circadian disruption in the triggering of obesity and MetS." (PMID 40115347, 2025). "Therefore, the aim of the present study is to investigate the association between variants in candidate genes—namely, BMAL1 rs7950226 (G>A), CLOCK rs1801260 (A>G), CLOCK rs4864548 (G>A), and CLOCK rs3736544 (G>A)—and overweight/obesity in 291 pregnant women." (PMID 38612648, 2024). "In addition, the current study is the first to evaluate the effect of energy distribution at meals on overweight or obesity in adolescents according to CLOCK rs3749474, rs4580704, and rs1801260 genotypes." (PMID 39744380, 2024).
Obesity (continued). "Although there are studies investigating the link between obesity and different SNPs in the CLOCK gene in various populations, findings regarding their relationship with anthropometric measurements, especially in the child and adolescent population, remain insufficient." (PMID 39744380, 2024). "In particular, rs7950226 (G>A) in the BMAL1 gene and rs1801260 (A>G), rs4864548 (G>A), and rs3736544 (G>A) in the CLOCK gene were reported to be significantly correlated with cardiovascular disease, obesity, metabolic syndrome, sleep reduction, and evening preference." (PMID 38612648, 2024). "The first model included genetic variants known to be associated with obesity—specifically, ADCY3 rs11676272, CLOCK rs1801260, GPR61 rs41279738, FTO rs1421085, RP11-775H9.2 rs1296328, SLC22A3 rs9364554, and TFAP2B rs734597—and explained 8.3% of the variance in BMI." (PMID 39766774, 2024). "Other studies have also shown associations between various CLOCK variants and obesity indicators, but they did not remain significant after correcting for multiple testing." (PMID 37761843, 2023). "Relationship between CLOCK SNPs and obesity.CLOCK rs1801260 may predict the outcome of body weight reduction strategies based on low-energy diets." (PMID 36768893, 2023). "The PubMed and Scopus databases were searched for studies reporting the association between circadian rhythm gene polymorphisms (ARNTL, BMAL1, CLOCK, CRY, PER, NPAS2, REV-ERBα, REV-ERBβ, and RORα) and MetS, and its comorbidities diabetes, obesity, and hypertension." (PMID 35053018, 2021). "BMAL1/CLOCK heterodimeric proteins are recognized as critical components of cellular circadian rhythm generation, which appear to be involved in liver disorders under obesity." (PMID 34943809, 2021). "Although it is unknown how Per1 and Per2 controls macrophage activation in obesity, the authors suggested a disruption in the feedback regulation of CLOCK/BMAL1 protein complex." (PMID 33371208, 2020). "CLOCK mutant mice exhibited abnormal diurnal feeding rhythm and obesity." (PMID 30379940, 2018). "Recently, CLOCK and PER2 polymorphisms have been linked to obesity and the metabolic syndrome." (PMID 30518396, 2018). "Conversely, the 3111T/C (rs1801260) in CLOCK protect against obesity and overweight only in women." (PMID 25089907, 2014). "Besides, genetic variations in CLOCK, PER2, and CRY1 increase the risk of obesity." (PMID 39351493, 2024). "Chronobiological aspects controlled by CLOCK genes may influence obesity incidence." (PMID 32575803, 2020). "Dysfunction of BMAL1, CLOCK and PPARγ may lead to obesity and metabolic syndrome." (PMID 20706650, 2010). "Previous GWASs have demonstrated the association of the studied polymorphic loci ADCY3 rs1167627272, CLOCK rs1801260, FTO rs1421085, GPR61 rs41279738, RP11-775H9.2 rs1296328, SLC22A3 rs9364554, and TFAP2B rs734597 with obesity-related phenotypes." (PMID 39766774, 2024). "We calculated the Hardy-Weinberg Equilibrium (HWE) for six genes (CLOCK, GHRL, FTO, LEP, LEPR, MC4R) related to obesity, using genotype frequencies from our dataset." (PMID 39203789, 2024). "Concerning the circadian clock, in the ANS/inflammation-induced obesity network constructed herein, ARNTL interacts with CLOCK, NR1D1 and CCRN4L." (PMID 39062927, 2024). "Metformin, an inhibitor of mTOR, can protect SIRT1 activity to maintain proper circadian rhythm of CLOCK and BMAL1 during obesity." (PMID 34356626, 2021). "In insulin-resistant mice, the perturbation of CLOCK, BMAL1, reduced c-erb-αoncogene (REV-ERBα) and Cryptochrome Circadian Clock 1 (CRY1) mRNA expression is evident during obesity." (PMID 33142938, 2020). "Hepatic mRNA expression of circadian (CLOCK, BMAL1, REV-ERBα, CRY, PER) and metabolic (PPARα, SIRT1) genes were strongly suppressed in offspring exposed to both maternal obesity and HFD." (PMID 24416203, 2014).
Obesity (continued). "Regarding CLOCK/CT, FTO/AT, GHRL/GT, LEP/GA, LEPR/AG, MC4R/CT we found intermediates values for weight, BMI, waist circumference, and WHR, reflecting moderate levels of body fat and obesity." (PMID 39203789, 2024). "It is conceivable that small molecules directly targeting CLOCK, such as CHX or similar agents, may have therapeutic efficacy toward mitigating obesity and Type II diabetes." (PMID 37525228, 2023). "A total of 39 overweight/obese Caucasian women (20 CLOCK 3111C carriers and 19 non-carriers) completed a behaviour–dietary obesity treatment of ~20 weeks, during which body weight was assessed weekly." (PMID 34371977, 2021). "CLOCK and BMAL are also critical in maintaining glucose homeostasis while Clock-mutant mice display phenotype of cardiovascular and metabolic diseases such as obesity and hypertension." (PMID 33050331, 2020). "However, in HFD-fed offspring AUC for CLOCK and BMAL1 mRNA were lowest in offspring from obese dams indicated by a significant interaction of maternal obesity and HFD consumption (p<0.001)." (PMID 24416203, 2014). "CLOCK and ARNTL disturbance may trigger obesity, hyperinsulemia and diabetes." (PMID 39062927, 2024). "Notably, individuals with the CLOCK (CC), FTO (AA), and LEP (AA) genotypes exhibited the highest BMI and WHR, while those with GHRL (TT), MC4R (CC), and LEPR (GG) genotypes, although showing lower values, were still correlated with overweight and obesity." (PMID 39203789, 2024). "Cryptochrome and period genes, as well as REV-ERBα1, constitute the second key components of the circadian system, responsible for the negative feedback loop that controls CLOCK/BMAL1 expression and have been also associated with metabolic and glycemic traits related to obesity and T2DM." (PMID 26927084, 2016). "Retinoic acid induced 1 (RAI1) transcriptionally regulates CLOCK, and haploinsufficiency of RAI1 is the primary contributor to the Smith-Magenis syndrome phenotype, a disorder characterized by circadian rhythm and sleep disruption, intellectual disability, and obesity." (PMID 27763782, 2016). "Without metformin, the absence of SIRT1 and mTOR block function of CLOCK and BMAL1 during obesity." (PMID 34356626, 2021).